RNU6-1212P (RNA, U6 small nuclear 1212, pseudogene)
Gene: Small nuclear RNA gene on chromosome 10 (19,792,998 to 19,793,101, reverse strand). Ensembl gene ENSG00000252832.
Homologues: Orthologues: chimpanzee U6 (99% identical), macaque U6 (88% identical), dog U6 (72% identical), mouse Gm25163 (59% identical), mouse Gm23044 (54% identical). Paralogues in human: RNU6-1181P (77% identical), RNU6-1251P (77% identical), RNU6-1039P (76% identical), RNU6-348P (76% identical), RNU6-468P (76% identical), RNU6-858P (76% identical), RNU6-591P (75% identical), RNU6-833P (75% identical), RNU6-878P (75% identical), RNU6-921P (75% identical), RNU6-1011P (74% identical), RNU6-1117P (74% identical), and 1286 more.